S100A1 (S100 calcium binding protein A1)
Diseases named in the same sentence as S100A1 in open-access papers (continued):
Sharing a sentence is not in itself a finding about the gene and the disease.
cancer (31 papers, 2011 to 2025). A tumor composed of atypical neoplastic, often pleomorphic cells that invade other tissues. "Collectively, these findings suggest that S100A1 is a pan-cancer oncogene and a promising diagnostic and prognostic biomarker for various tumors." (PMID 39742274, 2024). "The overexpression of S100A1 in cancer cells has been linked to several hallmarks of cancer, such as cell proliferation, survival, invasion, and metastasis." (PMID 37538932, 2023). "For example, S100A4 promotes EMT and cancer stem cell properties, while S100A1 influences cell cycle arrest and apoptosis." (PMID 41303754, 2025). "Both FGF13 and S100A1 have been suggested to promote cancer cell growth and survival by previous studies." (PMID 38791872, 2024). "Survival curve analysis based on TCGA dataset showed that the long-term prognosis was quite different between the S100A1 high and low groups, which suggested S100A1 can be used as a prognostic marker for cancer." (PMID 34475990, 2021). "S100A1 is also highly expressed in various cancer cells and participates in regulating important pathophysiological processes." (PMID 34475990, 2021). "The data presented here are very encouraging and elucidate the possibility of more customized development of S100A1 as a drug molecule against cancer development." (PMID 32497081, 2020). "Two metrics for IHC staining were used: the percentage of carcinoma with S100A1 staining (%Pos), and the product of the staining intensity (optical density [OD] of staining) multiplied by the percentage of carcinoma with S100A1 staining (OD*%Pos)." (PMID 22515559, 2012). "S100A1 has been found to be involved in the development and progression of cancer." (PMID 37538932, 2023). "We also studied the S100A4 as an inhibitor—it blocking the interface of the V domain and S100A1 to stop the cell proliferation and could be used as the treatment of cancer and RAGE related disease." (PMID 30779808, 2019). "Further studies are required to design S100B analogs that could potentially act as efficient blockers that disrupt the S100A1-RAGE V domain pathway for the treatment of various human cancers or inflammation diseases." (PMID 29444082, 2018). "As cancer cells are characterized by redox imbalance and oxidative stress is a major source of excess Zn2+ in cells (the oxidation of sulfhydryl groups in Zn2+-buffer proteins leads to massive Zn2+ release), S100A1 can predominantly act as a Zn2+-saturated conformer in cancer cells." (PMID 34944467, 2021). "Furthermore, our findings are essential to designing S100A4 analogs that may possibly act as effective blockers to inhibit the RAGE V domain-S100A1 route for the treatment of many kinds of human cancer and inflammation." (PMID 30779808, 2019). "Assessment of cardiotoxicity with S100A1 may be a valuable alternative in clinical oncology of cancers in some organs such as breast and prostate, as they do not overexpress it to compete against." (PMID 26682543, 2015). "Thus, S100A1 screening following the chemotherapy of these specific cancers may not accurately reveal cardiotoxicity." (PMID 26682543, 2015). "Based on the Oncomine database, there are no obvious distinctions in S100A1, S100A4, S100A5, S100A6, and S100A13 expressions between cancer tissues and normal colon mucosa, and S100A7, S100A12, and S100Z are slightly overexpressed in CRC tissues." (PMID 33294444, 2020). "Moreover, the pan-cancer analysis did not reveal a significant correlation between CD274 and S100A1 mRNA expression in multiple types of solid tumors." (PMID 40090947, 2025).
infection (11 papers, 2010 to 2025). The state of being infected such as from the introduction of a foreign agent such as serum, vaccine, antigenic substance or organism. "Infection with recombinant adenovirus expressing S100A1 re-established S100A1 levels to near normal in MiR-138 mimic transfected cells, and re-established tube formation capability." (PMID 24244340, 2013). "Similar to the cytokine TGFβ gene, the expression of the gene encoding S100A1 (involved in neurotransmitter signaling) was merely significantly elevated in the spleen at day 8 after infection, and not regulated in skin and gills at any sampling point." (PMID 31220151, 2019). "One-fifth of upregulated DEPs in the AD retinas were related to immune responses, including HLA-DRB1, APOC1, S100A1, HLA-E, IBA1, and S100β, and involved lymphocyte and myelomonocyte activation in the presence of neuroinflammation and infection." (PMID 36773106, 2023). "However, S100A1, MUC1, and TRIP6 showed a continued up-regulated status at 4 days post-infection." (PMID 21172007, 2010).
cardiovascular diseases (7 papers, 2013 to 2025). "Of note, S100A1 has attracted particular interest as a therapeutic target for cardiovascular diseases including heart failure, as such, further studies investigating the effects of this gene in PTCs are clearly justified." (PMID 39562547, 2024). "Plasma S100A1 was correlated with levels of hs-CRP, especially in patients with an elevated hs-CRP level (> 3mg/L), which is a relative higher risk for cardiovascular diseases." (PMID 31523180, 2019). "S100A1 is especially interesting with respect to cardiovascular diseases because downregulation of S100A1 protein critically contributes to the progressive contractile dysfunction of the diseased heart and cardiac-related death." (PMID 23683996, 2013).
cardiac disease (1 paper, 2021). "In rodent and pig cardiac disease models, adenoviral-associated vector S100A1 gene delivery to cardiac tissue normalized low S100A1 levels and restore cardiomyocytes physiologic contractility, restored cardiac performance, and left ventricular remodeling." (PMID 34239729, 2021).
S100A1 also shares sentences with these, for which no sentence is quoted: hepatocellular carcinoma (7 papers); neurodegenerative disease (5); COVID-19 (4); acute myocardial infarction (3); Alzheimer disease (3); Sepsis (3); bladder cancer (2); cervical cancer (2); coronary artery disease (2); esophageal cancer (2); Impaired glucose tolerance (2); nasopharyngeal carcinoma (2); neurological diseases (2); pulmonary hypertension (2); renal oncocytoma (2); rheumatoid arthritis (2); schizophrenia (2); systemic lupus erythematosus (2); acne (1); adenocarcinoma (1); adenomyosis (1); angina pectoris (1); angiomyolipoma (1); Arterial thrombosis (1); Arthritis (1); asthma (1); autoimmune disease (1); autoimmune pancreatitis (1); bacterial infection (1); chorioamnionitis (1).
A further 55 diseases each share a sentence with S100A1 in 1 paper.